AKT2 (AKT serine/threonine kinase 2)
Diseases named in the same sentence as AKT2 in open-access papers (continued):
Sharing a sentence is not in itself a finding about the gene and the disease.
colorectal cancer (21 papers, 2008 to 2025). A primary or metastatic malignant neoplasm that affects the colon or rectum. "PTEN loss is required for metastasis of colorectal cancer cells overexpressing AKT2." (PMID 28082369, 2017). "AKT1 may function as an oncogene and AKT3 as a tumor suppressor, and AKT mutations have been detected in human colorectal cancer (AKT2) and lung tumors (AKT1 and AKT3)." (PMID 24338765, 2014). "The present study attempts to explore the inhibitory impact of KA25 and KA39 derivatives on Akt1 and Akt2 phosphorylation in three colorectal cancer cell lines (HT-29, LoVo, and SW403) with specific PIK3CA and KRAS statuses." (PMID 33916378, 2021). "This work is based on knock-down and knock-out strategies—we more specifically characterized the importance of Akt isoforms Akt1 and Akt2 for homologous recombination repair of DSBs in human colorectal cancer cells in vitro." (PMID 31847370, 2019). "Taken together, based on the results presented, our study showed that Akt1 and especially Akt2 are involved in the regulation of homologous recombination in human colorectal cancer cells." (PMID 31847370, 2019). "In colorectal carcinoma, miR-194 inhibits cell viability and invasion via its actions on the AKT2 pathway." (PMID 26909612, 2016). "In a xenograft model of colorectal cancer, knockdown of Akt2 in KM20 cell line inhibits liver metastasis; the converse is observed when constitutively active Myr-Akt2 is expressed." (PMID 25302298, 2014). "We analysed melanoma clinical specimens for the presence of mutations in AKT1, AKT2, and AKT3 that result in the E17K mutation identified previously in breast, ovarian, and colorectal cancers." (PMID 18813315, 2008). "In addition, knockdown of AKT1 and AKT2 inhibited cell proliferation and colony growth by attenuating cell cycle progression and upregulating the apoptosis of colorectal cancer cells, similar to resveratrol treatment." (PMID 36430164, 2022). "Significant alterations have been demonstrated in the expression levels of Akt isoforms in certain malignancies, for instance, Akt1 is particularly elevated in breast, prostate, and gastric tumors whilst Akt2 is overexpressed in prostate, ovarian, breast, pancreatic, and colorectal cancers." (PMID 33916378, 2021). "Thus, our data demonstrate that both Akt1 and Akt2 are involved in double strand break repair via the HRR pathway in the HCT116 human colorectal cancer cell line." (PMID 31847370, 2019). "AKT2 is amplified in cancers such as ovarian (12.2%), breast (2.8%) and pancreatic cancers (10%) and its expression is elevated in pancreatic ductal adenocarcinomas and colorectal cancers." (PMID 28082369, 2017). "Thus, these authors demonstrated that the targeting of AKT1 and AKT2 by resveratrol could be a powerful strategy for chemoprevention or treatment for colorectal cancer." (PMID 36430164, 2022). "Thus, in the present study, we aimed to investigate the Akt-dependency of HR more specifically in HCT116 human colorectal cancer cells presenting knockout as well as knockdown phenotypes for the AKT-isoforms AKT1 and AKT2." (PMID 31847370, 2019). "To do this, we used human colorectal carcinoma cells with inactivated AKT1 and AKT2 genes." (PMID 31847370, 2019).
colorectal cancer (continued). "Two colorectal cancer cell lines, DLD-1 and HCT116, and their corresponding isogenic AKT isoforms knockout cell lines were used to show whether AKT1 or AKT2 were activated after exposure to ionizing radiation and their effect on the expression of MRE11 and DNA-PKcs." (PMID 24338765, 2014). "In this study, two colorectal cancer cell lines, HCT116 and DLD-1, were used in which the AKT isoforms, AKT1 and AKT2, have been knocked out with no residual protein expression, which enables the analyses of the different AKT isoforms to be more reliable." (PMID 24338765, 2014).
Hyperinsulinemia (21 papers, 2013 to 2025). An increased concentration of insulin in the blood. "Gene variations (p.G972R, and p.T608R) of insulin receptor substrate 1 (IRS-1), PI3K and (R274H, R208 K and R467W) and in AKT2 were reported to be associated with T2D, fasting hyperglycemia and postprandial hyperinsulinemia." (PMID 37754255, 2023). "Studies have found that Akt2 (R274H) mutation can cause severe hyperinsulinemia and DM in humans, which also shows that AKT actively participates in the in vivo regulation of metabolism." (PMID 35755045, 2022). "The observed hyperinsulinemia is largely a consequence of Akt2 inhibition, which is the major Akt isoform expressed in insulin-responsive tissues and particularly in the liver." (PMID 35578699, 2021). "Interestingly, treatment with the antidiabetic drug metformin did not have a significant effect on hyperinsulinemia induced by Akt2 deficiency." (PMID 35578699, 2021). "For instance, AKT-2, GSK-3β, GLUT1, and GLUT4 mRNA expression were upregulated in the hearts of hyperinsulinemic horses, suggesting that prolonged hyperinsulinemia induced an increase in insulin sensitivity in the heart, which could be cardioprotective." (PMID 32596266, 2020). "Interestingly, the diabetic drug metformin did not have any significant effect on hyperinsulinemia induced by systemic Akt2 deletion in mice." (PMID 35578699, 2021). "However, supplementation with TB protected IUGR piglets from hyperinsulinism and maintained normal metabolism of glycose in the liver of IUGR piglets, and the mRNA expression of INSR and Akt2 was downregulated which corresponded to the decreased concentration of insulin." (PMID 26317832, 2015).
cervical carcinoma (19 papers, 2006 to 2025). A carcinoma arising from either the exocervical squamous epithelium or the endocervical glandular epithelium. "Cervical cancer cells were transfected with AKT1 or AKT2 siRNA and subjected to irradiation treatment." (PMID 32711558, 2020). "We also demonstrated that overexpression of miR-2861 resulted in the suppression of EGFR/AKT2/CCND1 pathway in cervical cancer cells." (PMID 27364926, 2016). "Our study demonstrated that HDAC inhibitors, such as valproic acid and butyrate, induce apoptosis in HeLa cervical cancer cells by inhibition of gene expression of Akt1 and Akt2." (PMID 17156483, 2006). "Finally, hsa-miR-2861 functions as a tumor suppressor by targeting the EGFR/AKT2/CCND1 pathway in human papillomavirus type 16 E6-induced cervical cancer." (PMID 41496911, 2025). "AKT1 and AKT2 expression was present in all three cervical cancer cell lines (Fig. S4BCD)." (PMID 34469022, 2021). "Therefore, the activation of the EGFR/AKT2/CCND1 signaling pathway induced by HPV16 E6-deprivated miR-2861 expression in cervical cancer cells may, at least partially, explain the tumor suppression effects of miR-2861 in cervical cancer." (PMID 27364926, 2016). "In addition, a study demonstrated that the interaction of the E6 oncoprotein could also cause a decrease in the expression of a tsmiR, by which HPV16 E6 is able to decrease the level of miR-2861 expression, resulting in the suppression of the EGFR/AKT2/CCND1 pathway in cervical cancer cells." (PMID 33803022, 2021). "In summary, a new regulatory network was found, employing HPV16 E6, miR-2861, and the EGFR/AKT2/CCND1 signaling pathway to syntonize proliferation, apoptosis, and invasion in cervical cancer cells." (PMID 33803022, 2021). "In cervical cancer, a research group demonstrated that miR-2861 suppressed tumor cell growth and invasion by targeting EGFR/AKT2/CCND1 pathway." (PMID 32003757, 2020). "To elucidate the regulatory mechanisms of miR-2861 in cervical cancer, we identified, for the first time, EGFR, AKT2, and CCND1 as the targets of miR-2861 in both SiHa and CaSki cells." (PMID 27364926, 2016). "Meanwhile, overexpression of EGFR, AKT2, and CCND1 eliminate the effect of miR-2861 on cervical cancer cells." (PMID 27364926, 2016). "Further, we demonstrated a biological link among HPV16 E6, miR-2861, EGFR, AKT2, and CCND1 in cervical cancer cells." (PMID 27364926, 2016). "In summary, we delineates a novel regulatory network employing HPV16 E6, miR-2861, and EGFR/AKT2/CCND1 signaling pathway to fine-tune proliferation, apoptosis, and invasion in cervical cancer cells." (PMID 27364926, 2016). "Though EGFR, AKT2, and CCND1 are regulated by multiple factors, out data suggest that miR-2861 exhibits tumor suppressor role by suppressing multiple targets including EGFR, AKT2, and CCND1 in HPV16 positive cervical cancer cells." (PMID 27364926, 2016). "miR-148a also repressed proliferation of bladder cancer cells by establishing a positive feedback loop between ERBB3/AKT2/c-myc signaling and DNMT1 or by regulating expression levels of DNMT1 and undifferentiated embryonic cell transcription factor 1 (UTF1) in cervical cancer cells." (PMID 36959680, 2023). "This understanding of the single molecular pathway, HPV16 E6/miR-2861/EGFR/AKT2/CCND1, may provide a new insight into exploring additional strategies for cervical cancer therapy in the future." (PMID 33803022, 2021).
cervical carcinoma (continued). "Furthermore, we identified a new pathway employing miR-2861, EGFR, AKT2, and CCND1 that mediates HPV16 E6 induced initiation and progression of cervical cancer." (PMID 27364926, 2016). "This understanding of unique molecular pathway, HPV16 E6/miR-2861/EGFR/AKT2/CCND1, may provide the novel insight into the exploration of additional strategies for cervical cancer therapy in the future." (PMID 27364926, 2016). "Thus, we identified a new pathway employing miR-2861, EGFR, AKT2, and CCND1 that may mediate HPV16 E6 induced initiation and progression of cervical cancer." (PMID 27364926, 2016).
gastric cancer (19 papers, 2007 to 2025). A primary or metastatic malignant neoplasm involving the stomach. "In summary, the present hospital-based case-control study investigated associations between five selected potentially functional AKT1/AKT2 SNPs and gastric cancer risk." (PMID 26818920, 2016). "The present study evaluated the effect of five selected potentially functional SNPs of AKT1 and AKT2 on risk of gastric cancer." (PMID 26818920, 2016). "Akt1 gene amplification has been implicated in gastric carcinoma while Akt2 amplification has been linked with ovarian, pancreas, breast and stomach tumors." (PMID 24330834, 2013). "AKT2 mutations are much rarer than AKT1 mutations, although an AKT2 mutation has been observed before in gastric carcinoma, at a 2% frequency." (PMID 21781349, 2011). "Several human disorders, including gastric cancer, NIHL, and PCOS have been linked to rs2304186 AKT2 gene polymorphisms." (PMID 38577021, 2024). "For example, over-expression of miR-194 significantly inhibited the proliferation and migration of gastric cancer cells, and the enhanced expression of miR-194-5p promoted Gallbladder cancer cell proliferation by targeting AKT2 gene." (PMID 32997306, 2021). "Thereby lncRNA Sox2ot stimulates cell proliferation and metastasis of gastric cancer cells as well as tumor growth and metastasis in nude mice by sponging miR-194-5p and elevating AKT2." (PMID 32629426, 2020). "The tumor-suppressor miR-29s can inhibit the invasive ability of gastric cancer cells by targeting AKT2." (PMID 28404925, 2017). "Strong AKT2 protein expression can be strongly detected in all 9 gastric cancer cell lines but only one normal gastric mucosal tissue showed week AKT2 protein expression." (PMID 25288334, 2014). "In conclusion, our results underscore let-7b/g as important tumor-suppressive miRNAs in gastric cancer cells by directly targeting AKT2." (PMID 25288334, 2014). "We have demonstrated that let-7b/g targeted AKT2 and exerted tumor suppressor function in gastric cancer." (PMID 25288334, 2014). "In 28 pairs of primary gastric cancers, AKT2 mRNA expression showed upregulation in 19 (67.9%) tumor samples by normalization with its expression in adjacent non-tumorous tissues." (PMID 25288334, 2014). "AKT2 knockdown also decreased monolayer colony formation in gastric cancer cells to a significant level." (PMID 25288334, 2014). "Expression of AKT2 mRNA was up-regulated in 8 gastric cancer cell lines except SNU1 compared with normal gastric mucosal sample." (PMID 25288334, 2014). "Bioinformatic analysis of the TCGA STAD dataset revealed that AKT3, but not AKT1 or AKT2, is upregulated in the majority of E-cadherin-deficient gastric cancers." (PMID 31540244, 2019). "Moreover, AKT2 protein expression inversely correlated with miR-143-3p level in 42 pairs of gastric cancer samples using Pearson correlation analysis (r= −0.422, P=0.005)." (PMID 28404925, 2017). "CCK-8 assays showed that si-AKT2 inhibited gastric cancer proliferation." (PMID 28404925, 2017). "Furthermore, silencing of AKT2 induced cell apoptosis and suppressed gastric cancer cell migration and invasion." (PMID 28404925, 2017). "MiR-137, which is involved in gastric cancer tumorigenesis and metastasis, may regulate AKT2-related signaling pathways." (PMID 28404925, 2017). "Our data demonstrated that AKT2 is a direct downstream mediator of miR-143-3p in gastric cancer." (PMID 28404925, 2017). "To date, associations between AKT1 and AKT2 SNPs and risk of gastric cancer have not yet been clarified." (PMID 26818920, 2016). "All these findings support that the frequently down-regulated let-7b/g contributes to activation of AKT2 and gastric carcinogenesis which might has therapeutic potential in gastric cancer." (PMID 25288334, 2014). "We then examined the AKT2 mRNA and let-7b/g expression in 28 paired primary gastric cancer samples." (PMID 25288334, 2014).
gastric cancer (continued). "We showed that AKT2 was upregulated in gastric cancer and its knockdown suppressed gastric cancer cell proliferation, reduced monolayer colony formation and inhibited xenograft formation in vivo, resembling the tumor-suppressive effects of let-7b/g in gastric cancer cells." (PMID 25288334, 2014). "The AKT2 mRNA expression was negatively correlated with let-7b/g expression (let-7b, P = 0.001; let-7g, P = 0.021), suggesting let-7b/g downregulation might be, at least partly, responsible for the aberrant activation of AKT2 in gastric cancers." (PMID 25288334, 2014). "Western blot analysis revealed a reduction in AKT2 levels, suggesting that let-7b-5p sensitizes cells to PI3K/AKT pathway inhibition, which is consistent with previous observations in renal and gastric cancer models." (PMID 41303548, 2025). "The query confirmed that AKT is abnormal in gastric cancer cell lines; specifically, the AGS cell line showed an amplification in the AKT2 gene whereas other esophageal/stomach cell lines express other significant gene variations as missense mutations or deep deletions." (PMID 40076652, 2025). "We have previously shown that AKT3, but not AKT1 or AKT2, is upregulated in gastric cancers with low CDH1 expression and have identified an E-cadherin-AKT synthetic lethal relationship." (PMID 35406381, 2022). "The effects of AKT2 on gastric cancer cells have not been characterized." (PMID 28404925, 2017).
hepatocellular carcinoma (19 papers, 2014 to 2025). A malignant tumor that arises from hepatocytes. "Overexpression of NEAT1 and AKT2 promotes proliferation and invasion of hepatocellular carcinoma cells, inhibits apoptosis, and increases the invasive capacity of malignant cells." (PMID 41465470, 2025). "AKT2 is also overexpressed in approximately 55% of colorectal cancers and nearly 40% of hepatocellular carcinomas." (PMID 39614261, 2024). "For example, lncRNA TUG1 is considerably expressed in hepatoma cells and augments the invasion and migration of hepatocellular carcinoma through targeting the miR-137/AKT2 axis." (PMID 35874626, 2022). "MicroRNA-612 (miR-612) has been proven to suppress EMT, stemness, and tumor metastasis of hepatocellular carcinoma (HCC) via PI3K/AKT2 and Sp1/Nanog signaling." (PMID 32033570, 2020). "In hepatocellular carcinoma patients, miR-612 inhibits the metastasis and epithelial–mesenchymal transition of cancer cells by targeting the AKT2 gene." (PMID 31766385, 2019). "It has been shown that microRNA-137 suppresses tumor growth and metastasis in human hepatocellular carcinoma by targeting AKT2." (PMID 25426556, 2015). "Furthermore, genetic deletion of Akt1 and Akt2 in the mouse liver induces liver damage, inflammation, and paradoxically hepatocellular carcinoma (HCC)." (PMID 29687779, 2018). "MiR-302b inhibited cell cycle in human hepatocellular carcinoma by targeting AKT2." (PMID 29050238, 2017). "MiR-137 targeted AKT2 to suppresses tumor growth and metastasis in human hepatocellular carcinoma." (PMID 29050238, 2017). "The silencing of EGFR by miR-302b or siEGFR led to downregulation of proliferation-related proteins, such as AKT2, CCND1, and CDK2, and resulted in the inhibition of proliferation in hepatocellular carcinoma SMMC-7721 cells." (PMID 33688369, 2021). "Our previous study identified AKT1, AKT2 and AKT3 as unfavorable prognostic factors for patients with hepatocellular carcinoma (HCC)." (PMID 25424347, 2014). "Firstly, human hepatoma HepG2 cells were exposed to varying concentrations of unsaturated (oleate) fatty acid for 18 h, but oleate did not affect the expression of INSR, IRS-1, and Akt2." (PMID 28036389, 2016).